AOAH (acyloxyacyl hydrolase)
Description:
Removes the secondary (acyloxyacyl-linked) fatty acyl chains from the lipid A region of bacterial lipopolysaccharides. By breaking down LPS, terminates the host response to bacterial infection and prevents prolonged and damaging inflammatory responses (By similarity). In peritoneal macrophages, seems to be important for recovery from a state of immune tolerance following infection by Gram-negative bacteria (By similarity).
Tractability: Small molecule: a structure with a bound ligand is known. Antibody: UniProt places it where antibodies can reach, with high confidence; UniProt predicts a signal peptide or a membrane-spanning region; its Gene Ontology location is reachable by antibodies, with medium confidence. PROTAC: its protein half-life has been measured.
Gene: Protein-coding gene on chromosome 7 (36,509,308 to 36,724,549, reverse strand). Ensembl gene ENSG00000136250.
Subcellular location: Secreted; Cytoplasmic vesicle
Subcellular location (Human Protein Atlas): Vesicles; Endoplasmic reticulum; Predicted to be secreted
Gene Ontology:
Molecular function: acyloxyacyl hydrolase activity; calcium ion binding; protein binding; hydrolase activity, acting on ester bonds
Biological process: fatty acid metabolic process; lipopolysaccharide catabolic process; negative regulation of inflammatory response
Cellular component: cytoplasmic vesicle; extracellular region
Genetic constraint (gnomAD): Loss-of-function variants: 49 observed, 71 expected, observed/expected ratio (o/e) 0.69, 90% interval 0.55 to 0.88. The upper end of that interval is the gene's LOEUF score, 0.88, which puts it in group 3 of 6, group 1 being the genes least tolerant of losing a copy. Missense variants: 551 observed, 615.5 expected, observed/expected ratio (o/e) 0.9, 90% interval 0.83 to 0.96. Synonymous variants: 229 observed, 230.61 expected, observed/expected ratio (o/e) 0.99, 90% interval 0.89 to 1.11.
Homologues: Orthologues: macaque AOAH (91% identical), dog AOAH (84% identical), pig AOAH (83% identical), mouse Aoah (76% identical), rabbit AOAH (76% identical), rat Aoah (76% identical), tropical clawed frog aoah (52% identical).
Diseases named in the same sentence as AOAH in open-access papers:
AOAH is named in the same sentence as 36 diseases in open-access papers, as found by Europe PMC text mining. Sharing a sentence is not in itself a finding about the gene and the disease. The quoted sentences say what the papers report.
asthma (4 papers, 2012 to 2021). "AOAH polymorphisms are reportedly associated with asthma, chronic rhinosinusitis, and bronchial hyperreactivity." (PMID 34020649, 2021). "To date, genetic linkage studies have found associations between polymorphisms in the AOAH gene and rhinosinusitis (confirmed in 2 populations of different ethnic composition) as well as asthma in humans." (PMID 23675296, 2013). "Supporting a role in airway disease, the AOAH gene has previously been implicated in a genome wide scan for asthma." (PMID 22723975, 2012). "In human studies, single nucleotide polymorphisms in the AOAH gene have been shown to be associated with asthma and chronic rhinosinusitis in Chinese and Canadian Caucasian populations, suggesting that AOAH may regulate some pulmonary inflammatory responses in humans." (PMID 28622363, 2017).
chronic rhinosinusitis (3 papers, 2017 to 2021). Chronic form of sinusitis. "Likewise, AOAH has been implicated in chronic rhinosinusitis." (PMID 32925915, 2020). "Thus, any alteration to AOAH-dependent AA homeostasis has the potential to alter normal eicosanoid balances and cell-cell interactions in chronic rhinosinusitis." (PMID 32925915, 2020).
Sepsis (3 papers, 2016 to 2023). Sepsis is defined as life-threatening organ dysfunction caused by a dysregulated host response to infection. "However, little is known regarding the role of AOAH in sepsis-induced hepatocyte injury or the regulation of AOAH expression." (PMID 32332915, 2020). "Thus, after CLP induced polymicrobial sepsis at 24 h and 48 h, the liver protein levels of TLR4 and of AOAH were determined and shown markedly decreased in CETP as compared to WT." (PMID 27293313, 2016).
ulcerative colitis (3 papers, 2011 to 2020). An inflammatory bowel disease involving the mucosal surface of the large intestine and rectum. "Trans-eQTL studies found that AOAH expression was linked to numerous SNPs associated with chronic inflammatory diseases, such as rheumatoid arthritis and ulcerative colitis, suggesting a role in chronic inflammation." (PMID 32925915, 2020). "These include a reported GWAS SNP for ulcerative colitis in the MHC class II region associated with expression of AOAH, a gene encoding the enzyme acyloxyacyl hydrolase which plays a key role in the inflammatory response to Gram-negative bacteria located on chromosome 7p14." (PMID 23122694, 2013).
gram-negative bacterial infections (2 papers, 2017 to 2020). Infections caused by bacteria that show up as pink (negative) when treated by the gram-staining method. "Thus, the role of AOAH in HIV infections is somewhat paradoxical as PLWH are more susceptible to secondary infections, yet AOAH is associated with protection from gram-negative bacterial infections, at least in murine studies." (PMID 32194550, 2020). "Inactivation of LPS by AOAH is a previously unappreciated mechanism for promoting resolution of pulmonary inflammation/injury induced by Gram-negative bacterial infection." (PMID 28622363, 2017). "AOAH prevents prolonged responses to LPS when overexpressed in mouse DC and protects mice from inflammation-induced injury during gram-negative bacterial infections as well as from gram-negative bacterial infection." (PMID 32194550, 2020).
metastatic melanoma (2 papers, 2020 to 2023). A melanoma that has spread from its primary site to another anatomic site. "CYTH4, DENND1C, AOAH, EPSTI1, and TBC1D10C expressions are upregulated in metastatic melanoma compared to primary tumors." (PMID 36588164, 2023).
psoriasis (2 papers, 2022 to 2023). An autoimmune condition characterized by red, well-delineated plaques with silvery scales that are usually on the extensor surfaces and scalp. "In this study, we used immunofluorescence of skin and ELISpot analyses of CD1a‐reactive T cells to investigate the role of the lipase acyloxyacyl hydrolase (AOAH) in CD1a ligand generation with relevance to the pathogenesis of psoriasis." (PMID 34913478, 2022). "Given the known expression of AOAH in neutrophils and other immune cells, we reasoned that AOAH may be upregulated in psoriatic lesions and sought to explore the role of AOAH and CD1a‐reactive T‐cell responses in the pathogenesis of psoriasis." (PMID 34913478, 2022). "Thus, the PLA2 activity of AOAH may also contribute to psoriasis pathogenesis." (PMID 37696897, 2023). "AOAH showed increased expression in lesional skin, compared to both uninvolved skin from the same donors and individuals with no psoriasis (GEO dataset ID GSE13355)." (PMID 34913478, 2022). "The findings in this study further support the role of nonpeptide antigens in psoriasis as key activators of T cells, and PLA2 activity of AOAH as a significant contributing factor to the disease pathogenesis." (PMID 34913478, 2022).
Anxiety (1 paper, 2022). Intense feelings of nervousness, tension, or panic often arise in response to interpersonal stresses. "In addition, AOAH-deficient mice exhibit neophobia and anhedonia-like behaviors, both of which are associated with anxiety and depression, thus drawing additional parallels with IC/BPS." (PMID 35980963, 2022).
atherosclerosis (1 paper, 2020). A disease characterized by the build-up of fatty material and calcium deposition in the arterial wall resulting in partial or complete occlusion of the arterial lumen. "Similarly, cardiovascular disease has an inflammatory component, and AOAH SNPs have been associated with carotid intima-media thickening, a marker of atherosclerosis." (PMID 32925915, 2020).
colitis (1 paper, 2013). Inflammation of the colon. "In addition, two studies of large populations have independently found that AOAH mRNA expression is associated in trans with polymorphisms in HLA-DRB1 that, in turn, have been strongly linked to colitis and primary biliary cirrhosis." (PMID 23675296, 2013).
E. coli infection (1 paper, 2017). "Our previous studies have shown that AOAH limits LPS-induced innate antibody production, prevents hepatosplenomegaly, and shortens endotoxin tolerance; overexpression of AOAH protects mice from E. coli infection." (PMID 28622363, 2017).
fibrosis (1 paper, 2024). the formation of excess fibrous connective tissue in an organ or tissue in a reparative or reactive process. "In addition, while previous research of AOAH has often focused on its classical enzymatic activity in the LPS model 19-22, 38, there is limited information available regarding a potential role of AOAH in non-microbial organ fibrosis." (PMID 38904010, 2024).
lung carcinoma (1 paper, 2020). "However, treatment of lung carcinoma cell cultures with a CoA-independent transferase inhibitor enhanced accumulation of free AA, consistent with our own findings associated with AOAH deficiency in vivo." (PMID 32925915, 2020).
melanoma (1 paper, 2023). A malignant, usually aggressive tumor composed of atypical, neoplastic melanocytes. "In addition to melanoma, CYTH4, AOAH, DENND1C, TBC1D10C, EPSTI1, SERPINB8, and GIMAP7 stratify responders and non-responders to ICB in other cancer types." (PMID 36588164, 2023). "CYTH4, DENND1C, AOAH, TBC1D10C, EPSTI1, GIMAP7, and FASL (FAS ligand) were novel predictors of ICB therapy and displayed high level of correlations with multiple immune checkpoints in melanoma and across 30 human cancers." (PMID 36588164, 2023).
renal fibrosis (1 paper, 2024). A final common manifestation of a wide variety of chronic kidney diseases characterized by glomerulosclerosis and tubulointerstitial fibrosis. "Here we present evidences for the first time that AOAH exerts a protective effect against renal fibrosis independently of acyloxyacyl hydrolase activity." (PMID 38904010, 2024). "Finally, AOAH expression was found positively correlated with estimated glomerular filtration rate while negatively correlated with the degree of renal fibrosis in kidneys of CKD patients." (PMID 38904010, 2024). "Therefore, targeting kidney AOAH represents a promising strategy to prevent renal fibrosis progression." (PMID 38904010, 2024). "Furthermore, we performed a preliminary exploration and found that AOAH expression in kidneys was positively correlated with estimated glomerular filtration rate (eGFR) but negatively with the degree of renal fibrosis in CKD patients." (PMID 38904010, 2024). "Targeting kidney AOAH represents a promising strategy to prevent renal fibrosis progression." (PMID 38904010, 2024). "Our results have suggested that AOAH protected against renal fibrosis by inhibiting CD74 signaling pathway, the precise mechanism underlying the interaction between AOAH and CD74, however, remains unknown." (PMID 38904010, 2024). "We further determined that AOAH expression was positively correlated with eGFR but negatively correlated with the degree of renal fibrosis." (PMID 38904010, 2024). "AOAH expression was positively correlated with eGFR but negatively with the degree of renal fibrosis in CKD patients." (PMID 38904010, 2024). "In this study, we determined the expression of AOAH in human kidneys and established a positive relationship between AOAH expression and eGFR, and showed a negative relationship between AOAH expression and the extent of renal fibrosis." (PMID 38904010, 2024). "Here, we have demonstrated increased CD74+ PTECs as well as elevated CD74 expression in FA-induced renal injury model with the lack of Aoah, and suggested that AOAH plays a protective role in renal fibrosis by inhibiting CD74 signaling pathways." (PMID 38904010, 2024).
infection (4 papers, 2020 to 2024). The state of being infected such as from the introduction of a foreign agent such as serum, vaccine, antigenic substance or organism. "Research shows that AOAH plays a critical role in infections and chronic inflammatory diseases, although its role in kidney injury is unknown." (PMID 38904010, 2024).
cancer (2 papers, 2023). A tumor composed of atypical neoplastic, often pleomorphic cells that invade other tissues. "In a comparison to AXL with an established role in enhancing resistance to ICB, CYTH4, DENND1C, AOAH, EPSTI1, and TBC1D10C display a stronger correlation with immune checkpoints in human cancers." (PMID 36588164, 2023). "For example, AOAH (a lipase acyloxyacyl hydrolase) and MAML2 (a transcriptional coactivator in the NOTCH-signaling pathway) are commonly downregulated in all cancers." (PMID 37024957, 2023). "CYTH4, AOAH, DENND1C, TBC1D10C, EPSTI1, SERPINB8, and GIMAP7 are novel and robust individual genes in predicting resistance to ICB in multiple cancer types." (PMID 36588164, 2023). "Additionally, CYTH4, DENND1C, AOAH, EPSTI1, and TBC1D10C exhibit strong correlations with a set of immune checkpoints not only in SKCM but also across a spectrum of human cancers." (PMID 36588164, 2023).
inflammation (1 paper, 2017). Aberrant reaction of the microcirculation characterized by movement of fluid and leukocytes from the blood into extravascular tissues. "Although intranasally administered hydrochloric acid (HCl) can also induce lung inflammation, AOAH expression was not significantly increased, suggesting that AOAH expression in AMs may be specifically induced by LPS and certain other MAMPs." (PMID 28622363, 2017).
kidney (1 paper, 2024). "We performed a rescue experiment by constructing an adenovirus (Ad) expressing Aoah to further verify the effects of AOAH in FA-induced kidney injury." (PMID 38904010, 2024).
AOAH also shares sentences with these, for which no sentence is quoted: Cardiovascular Disease (2 papers); tumor (2); Alzheimer disease (1); amyloidosis (1); colon cancer (1); depression (1); endotoxemia (1); glioma (1); interstitial cystitis (1); kidney injury (1); myocardial infarction (1); papillary thyroid carcinoma (1); primary biliary cirrhosis (1); rheumatoid arthritis (1); rhinosinusitis (1); thyroid cancer (1); urinary tract infection (1).